APOM (apolipoprotein M)
Description:
Probably involved in lipid transport. Can bind sphingosine-1-phosphate, myristic acid, palmitic acid and stearic acid, retinol, all-trans-retinoic acid and 9-cis-retinoic acid.
Synonyms: Apo-M; G3A; NG20; HSPC336
Tractability: Small molecule: a structure with a bound ligand is known; it has a binding pocket of medium quality. Antibody: UniProt places it where antibodies can reach, with high confidence; its Gene Ontology location is reachable by antibodies, with high confidence; UniProt predicts a signal peptide or a membrane-spanning region.
Gene: Protein-coding gene on chromosome 6 (31,652,416 to 31,658,210, forward strand). Ensembl gene ENSG00000204444.
Subcellular location: Secreted
Subcellular location (Human Protein Atlas): Golgi apparatus; Predicted to be secreted
Pathways (Reactome):
Sensory Perception: Retinoid metabolism and transport
Gene Ontology:
Molecular function: antioxidant activity; lipid transporter activity; phospholipid binding; molecular carrier activity
Biological process: cholesterol efflux; high-density lipoprotein particle remodeling; negative regulation of plasma lipoprotein oxidation; cholesterol homeostasis; high-density lipoprotein particle assembly; high-density lipoprotein particle clearance; retinoid metabolic process; reverse cholesterol transport; cellular oxidant detoxification
Cellular component: discoidal high-density lipoprotein particle; high-density lipoprotein particle; low-density lipoprotein particle; spherical high-density lipoprotein particle; very-low-density lipoprotein particle; extracellular region
Genetic constraint (gnomAD): Loss-of-function variants: 24 observed, 23.48 expected, observed/expected ratio (o/e) 1.02, 90% interval 0.74 to 1.44. The upper end of that interval is the gene's LOEUF score, 1.44, which puts it in group 5 of 6, group 1 being the genes least tolerant of losing a copy. Missense variants: 200 observed, 234.66 expected, observed/expected ratio (o/e) 0.85, 90% interval 0.76 to 0.96. Synonymous variants: 82 observed, 82.66 expected, observed/expected ratio (o/e) 0.99, 90% interval 0.83 to 1.19.
Homologues: Orthologues: chimpanzee APOM (99% identical), macaque APOM (95% identical), pig APOM (90% identical), rabbit APOM (90% identical), dog APOM (87% identical), guinea pig APOM (83% identical), mouse Apom (81% identical), rat Apom (71% identical), tropical clawed frog apom (45% identical).
Diseases named in the same sentence as APOM in open-access papers:
APOM is named in the same sentence as 118 diseases in open-access papers, as found by Europe PMC text mining. Sharing a sentence is not in itself a finding about the gene and the disease. The quoted sentences say what the papers report.
atherosclerosis (33 papers, 2012 to 2025). A disease characterized by the build-up of fatty material and calcium deposition in the arterial wall resulting in partial or complete occlusion of the arterial lumen. "Although, disturbed apoM/S1P regulation has been linked to endothel dysfunction and atherosclerosis, data on apoM and S1P levels in AGHD is currently lacking." (PMID 41268158, 2025). "Hyperlipidaemia and diabetes are proven risk factors for NTDs; ApoM is associated with both conditions, as well as with atherosclerosis and cardiovascular disease." (PMID 39827160, 2025). "Apolipoprotein M (apoM), as a novel apolipoprotein which is mainly expressed in liver and kidney tissues, is associated with development and progression of atherosclerosis and diabetes." (PMID 24642298, 2014). "However, ApoM deficiency leads to lipid deposition and metabolic distress and promotes atherosclerosis." (PMID 33830664, 2021). "However apoM has profound effects on both VLDL/LDL metabolism and S1P that also interfere with atherosclerosis, and the net effect of apoM (if any) on cardiovascular disease (CVD) risk in humans is unresolved." (PMID 23439550, 2013). "Hence, most studies on apoM so far have investigated its effect on and association with lipid metabolism and atherosclerosis." (PMID 23439550, 2013). "Thus, reduced levels of APOM, with its antioxidant, endothelium-protective, and antiatherogenic properties, may contribute to the increased susceptibility to atherosclerosis seen in patients with CKD." (PMID 40047074, 2025). "It has to be noted that extreme overexpression of APOM in LDL receptor knockout mice accelerated atherosclerosis, likely due to the concomitant increase in lipid levels." (PMID 40047074, 2025). "ApoM appears to limit pyroptosis and improve inflammation in human umbilical vein endothelial cells during atherosclerosis." (PMID 39827160, 2025). "APOM, secreted by the liver, is often bound to HDL in circulation, and was associated with reduced atherosclerosis in mouse models." (PMID 37400771, 2023). "A recent observation indicated lncRNA TUG1 regulates ApoM to promote atherosclerosis progression through miR-92a/FXR1 axis." (PMID 34057025, 2021). "For example, a hub protein, apolipoprotein M (encoded by APOM), is a key regulator of high-density lipoprotein metabolism that subsequently modulates the efflux of cholesterol and atherosclerosis susceptibility." (PMID 34230558, 2021). "Resveratrol, a proposed supplement to prevent atherosclerosis, is reported to modulate S1P levels by affecting ApoM levels." (PMID 31379883, 2019). "Altogether, the decreased apoM levels in patients with active lupus nephritis seen in our study fit well with the previous findings of dyslipidemia and atherosclerosis in SLE patients with renal involvement." (PMID 31046824, 2019). "ApoM levels are subjected to variations, with drastically reduced amounts during diseases such as atherosclerosis, coronary artery disease, or myocardial infarction as well as acute phase responses." (PMID 31379883, 2019). "Recent studies have suggested that apolipoprotein M (ApoM), a carrier protein for S1P, modulates the biological properties of S1P in the pathogenesis of atherosclerosis." (PMID 29301231, 2017). "This review will focus on the putative biological roles of the new apoM–S1P axis in relation to lipoprotein metabolism, lipid disorders and atherosclerosis." (PMID 23439550, 2013). "The effects of apoM and the bioactive S1P (and its five receptors) on lipid metabolism and atherosclerosis are still poorly understood." (PMID 23439550, 2013). "Further, overexpression of ApoM in LDL-receptor knockout mice protects against atherosclerosis in mice fed a cholesterol-rich diet." (PMID 23216709, 2012).
atherosclerosis (continued). "The ApoM-S1P axis is thus central to the maintenance of endothelial homeostasis, and its disruption contributes to the pathophysiology of endothelial dysfunction and atherosclerosis." (PMID 41303567, 2025). "Accumulating evidence suggests that ApoM improves mitochondrial function, exerts anti-apoptosis and antioxidative effects and participates in pathological processes (including diabetic nephropathy and atherosclerosis)." (PMID 39827160, 2025). "These suppressive effects of S1P-ApoM-HDL are absent with ApoM deficient HDL and levels of S1P-ApoM-HDL have been shown to be much lower in inflammatory cardiovascular diseases including atherosclerosis and T2DM." (PMID 39408263, 2024). "Since a role of apoM-S1P complex in prevention of endothelial dysfunction and atherosclerosis has been suggested, we wanted to investigate if lower apoM levels in SLE could contribute to endothelial dysfunction." (PMID 31046824, 2019). "By affecting the immune and anti-inflammatory functions of HDL,8, 9 ApoM may reduce atherosclerosis-related inflammation, preventing the onset and development of atherosclerosis." (PMID 27841911, 2016). "However, it is important to consider the inhibition of apoM expression by DHC when it was used as the therapeutic drug for atherosclerosis and diabetes." (PMID 24642298, 2014). "The mechanism by which apoM may protect against atherosclerosis may involve effects on lipid metabolism, including increased pre-β HDL formation, increased cholesterol efflux from foam cells and protection of HDL against oxidation." (PMID 23439550, 2013). "Over expression of ApoM had a protective effect against atherosclerosis." (PMID 24040766, 2013). "In murine models, apoM overexpression enhances HDL function and cholesterol efflux, thereby reducing atherosclerosis." (PMID 41303567, 2025). "TUG1 is extensively linked with several cholesterol efflux genes, including apolipoprotein M (ApoM), ABCA1, and ABCG1, and consequently with atherosclerosis." (PMID 39273193, 2024). "Studies in genetically modified mice and in vitro indicate that apoM has several potentially beneficial effects on pre-β HDL formation, oxidation of lipids, cholesterol efflux and atherosclerosis." (PMID 23439550, 2013). "With the discovery of apoM as a carrier of S1P on HDL particle, new links between lipoproteins, endothelial function and atherosclerosis can be explored, and this will be the topic of the remaining part of this review." (PMID 23439550, 2013). "This suggests that apoM has not only positive but also negative effects on atherosclerosis progression." (PMID 32872588, 2020). "On the other hand, even though plasma ApoM was reduced in patients with metabolic syndrome, it failed to predict subclinical atherosclerosis." (PMID 31842389, 2019). "Apolipoprotein M (ApoM) is a newly discovered apolipoprotein which has a special structure and is considered to play an important role in the metabolism of HDL and the anti-atherosclerosis process." (PMID 27206623, 2017). "Moreover, S1P elevation in Apoe–/– mice overexpressing apoM augmented aortic root but not aortic arch atherosclerosis, and this effect was abolished in uremia." (PMID 39531328, 2024). "Overall these data suggest that S1P-bound ApoM, rather than total S1P bound to other carriers, such as albumin, could be critical in conferring protection against atherosclerosis." (PMID 31842389, 2019).
atherosclerosis (continued). "However neither apoE nor apoM were altered in CKDpatients, even in CKD5 patients with the most advanced atherosclerosis." (PMID 27600335, 2016).
diabetes (30 papers, 2013 to 2026). "This study aims to explore the association between plasma apolipoprotein M (apoM) levels and diabetic retinopathy in patients with type 2 diabetes mellitus (T2DM)." (PMID 42051463, 2026). "A pioneering study based on the mapping of proteins and genes encoded in the human chromosome 6 in the major histocompatibility complex region suggested a genetic association between apoM and diabetes." (PMID 34093440, 2021). "SNP in the human APOM gene and its association with changes in plasma apoM levels and risk of diabetes." (PMID 34093440, 2021). "Hopefully, it will be confirmed in future studies if apoM, S1P, and/or their complex play potential roles in the development of diabetes or as a target in the treatment of either diabetes or the multiple associated conditions." (PMID 34093440, 2021). "This study investigated the correlation of four single nucleotide polymorphisms (SNPs) in Apolipoprotein M (ApoM) with the risk of type 2 diabetes mellitus (T2DM) and effects of the interactions of this gene and obesity." (PMID 32398715, 2020). "One group of genes (SERPINA12, CPE, SERPINA11, MTCH2, PNPLA5, INTS1, APOM) was associated (cosine value >0.1) with obesity and diabetes." (PMID 23544116, 2013). "It was evaluated whether changes in the plasma apoM or S1P levels were associated with prevalent subclinical atherosclerosis in 545 individuals from the African American Diabetes Heart Study." (PMID 34093440, 2021). "The difference in apoM levels was largely attributable to diabetes-associated obesity." (PMID 34093440, 2021). "Lastly, as indicated by the evaluation of the genetic studies published, the hypothesis that a reduction in plasma apoM expression at the gene level is associated with an increased risk of diabetes is yet to be confirmed." (PMID 34093440, 2021). "Hypothetically, SNPs in the human apoM gene that reduce the apoM levels, and resultantly, the S1P levels, could lead to a permanent reduction in S1P-signaling and diabetes risk." (PMID 34093440, 2021). "apoM is also associated with hyperlipidaemia and type 2 diabetes mellitus (T2DM)." (PMID 27633510, 2016). "Therefore, low plasma apoM levels in T2DM patients were likely caused by diabetes but were unlikely induced by hyperlipidaemia." (PMID 27633510, 2016). "Therefore, the specific effect of hyperlipidaemia on plasma apoM in patients with T2DM should be investigated to confirm whether low plasma apoM levels in T2DM are caused by diabetes or hyperlipidaemia." (PMID 27633510, 2016). "Moreover, both in vivo and in vitro observations suggested that ApoM may also be associated with diabetes and obesity." (PMID 25144649, 2014). ",26,28, 29, 30 ApoM also represents an important connection between diabetes and HF with preserved ejection fraction, a condition where SGLT2i recently demonstrated benefits." (PMID 40579057, 2025). "Mice models of T2D with hyperinsulinemia display lower plasma APOM levels compared with controls, but streptozotocin-induced diabetes raised plasma APOM." (PMID 39303980, 2024). "It is interesting that plasma ApoM levels are low in subjects with type 2 diabetes mellitus (T2DM), a phenomenon that, according to some authors, is likely caused by diabetes and is not a consequence of the dyslipidemia that often accompanies T2DM." (PMID 36980195, 2023). "At present, many studies have shown that the APOM gene is related to diabetes, dyslipidemia, obesity, and other diseases, which are high-risk factors leading to MI." (PMID 37065492, 2023). "It has been reported that individuals with type 2 diabetes have low total plasma ApoM and S1P levels and that total plasma ApoM and S1P levels are inversely correlated with mortality in patients with diabetes." (PMID 35104242, 2022). "The onset of diabetes makes it more challenging to identify the precise role of apoM owing to its contribution in dyslipidemia, insulin resistance, and inflammation, which potentially affects the plasma levels of apoM." (PMID 34093440, 2021).
diabetes (continued). "Further, a recent study in adipose tissue showed that apolipoprotein M expression was decreased in T2D and obese individuals compared to lean individuals, further indicating a role for downregulation of genes in diabetes pathogenesis." (PMID 34134627, 2021). "This review focuses on the roles of apoM and S1P in diabetes and our learnings from human and animal studies." (PMID 34093440, 2021). "As a biomarker for diabetes, it is likely that plasma apoM can be used to distinguish between patients with MODY3 and T1D but not T2D." (PMID 34093440, 2021). "Recent studies have also addressed the role of apoM and S1P in the development of diabetes and obesity." (PMID 34093440, 2021). "The following section will focus on the role of apoM/S1P in the development of experimental diabetes." (PMID 34093440, 2021). "The role of the apoM/S1P complex as a biomarker, the effect of diabetes on the plasma apoM/S1P levels, and the potential role of apoM/S1P in the development of diabetes have been discussed." (PMID 34093440, 2021). "The plasma concentration of ApoM was decreased in a study with patients with type 2 diabetes mellitus but was unchanged in another study." (PMID 31842389, 2019). "Diabetes is the possible reason for low plasma apoM levels in patients with type 2 diabetes mellitus, but are not induced by hyperlipidemia." (PMID 28877724, 2017). "Glucose concentrations, glucose metabolic products, and diabetes pathogenesis can influence apoM metabolism." (PMID 27633510, 2016). "The apoM promoter variant T-778C is associated with an increased risk of T2DM and is susceptible to type 1 diabetes mellitus." (PMID 27633510, 2016). "Multivariate analyses showed that diabetes itself was an independently inhibiting factor for plasma apoM levels." (PMID 27633510, 2016). "The link between apoM and type 2 diabetes mellitus (T2DM) has also been investigated by using in vivo and in vitro models." (PMID 27633510, 2016). "Multivariate linear regression analysis showed that hyperlipidaemia (β = 5.18, P = 0.007) is an independent promoting factor of plasma apoM levels and diabetes (β = −3.09, P = 0.005) is an inhibiting factor of plasma apoM levels." (PMID 27633510, 2016). "Hepatic apoM gene expression and plasma level were significantly low in mouse models of alloxan-induced diabetes and hyperglycaemia-induced diabetes." (PMID 27633510, 2016). "S1P and ApoM have also been investigated in experimental models of insulin resistance and diabetes." (PMID 35104242, 2022). "In patients with diabetes, the ApoM level is significantly reduced, and the rescue of ApoM level can decrease blood sugar level, increases insulin secretion, and improves insulin resistance, thereby serving as a predictor of the development of diabetes." (PMID 33490085, 2020). "Additionally, diabetes has been shown to influence apoM levels as shown by decreased S1P and apoM plasma levels in type 2 diabetic patients." (PMID 33260660, 2020). "Instead, low plasma apoM levels were likely triggered by diabetes." (PMID 27633510, 2016). "Besides, the plasma apoM levels were higher in streptozotocin-induced diabetes mice than those in control mice." (PMID 27633510, 2016). "The plasma apoM levels were decreased obviously in patients with type 2 diabetes mellitus (T2DM)." (PMID 27576735, 2016). "Diabetes was also an independent inhibiting factor of plasma apoM levels." (PMID 27633510, 2016). "Low plasma apoM levels in patients with T2DM are likely caused by diabetes but are not induced by hyperlipidaemia." (PMID 27633510, 2016). "It has been suggested that apoM may associate with coronary heart disease (CHD), diabetes and other diseases with dyslipidemia." (PMID 26377577, 2015). "In humans, it is unclear whether HDL-ApoM-S1P critically contributes to diabetes development, since several genetic variants in the promoter region of ApoM are not linked to increased diabetes risk." (PMID 35362476, 2022).